JAK1 (Janus kinase 1)
Diseases named in the same sentence as JAK1 in open-access papers (continued):
Sharing a sentence is not in itself a finding about the gene and the disease.
infection (continued). "Notably, the majority chemokine ligand, which induced cells of the immune system to enter the site of infection, CCL-2, CD80 and CD68 of TAMs, IRF5 and NOS2 of M1, CD163 and MS4A4A of M2 were strongly related to JAK1 expression in LUAD (all P value < 0.0001)." (PMID 34587898, 2021). "MiR-30c has a negative effect on the IFN-I response by targeting Janus kinase 1 (JAK1) to facilitate HP-PRRSV of genotype 2 infection." (PMID 33918746, 2021). "The results showed that FCV 2280 infection contributed to the decrease of JAK1 and Tyk2 phosphorylation but did not reduce the expression levels of total JAK1 and Tyk2." (PMID 33075108, 2020). "Notably, the transcription of JAK1 and STAT1 was enhanced both in the acute and the slow infection models." (PMID 32664675, 2020). "Enhanced JAK1 expression was also seen in OQ01 and BHY 6 and 24 h post-infection." (PMID 33391626, 2020). "The expression of STAT1, JAK1, and JAK2 genes increased following the infection time." (PMID 33240261, 2020). "Without IFNα activation, only a minor fraction of JAK1 in Mock-infected cells were phosphorylated (pJAK1/JAK1 = 0.15) compared with IFN-treated Mock-infected cells and neither Tha nor Th2P infection impaired that level of JAK1 phosphorylation." (PMID 31434934, 2019). "We show that in JAK1-expressing cells, IL-6 sensitized PCa cells to viral cell death in the presence or absence of productive infection, with dependence on virus employed." (PMID 29441069, 2018). "Infection of LNCaP-JAK1 cells in the presence of IL-6 (5 ng/mL), however, resulted in near complete abrogation of NS3 expression, suggesting a strong antiviral effect of this cytokine in JAK1-expressing cells." (PMID 29441069, 2018). "Taken together, restoration of JAK1 expression in LNCaP cells restored IFNα signaling, exposed the cells to IFNα-mediated growth inhibition, and allowed for the cytoprotective, antiviral effects of IFNα, resulting in a block of EHDV-TAU infection." (PMID 29441069, 2018). "JAK1, JAK2, JAK3, and Tyk2 all became more phosphorylated after infection of ST cells by TGEV." (PMID 28642467, 2017). "UPEC colonization in prostate cells co-incubated with testosterone and JAK1 or STAT1 inhibitor did not decrease 24 h after the infection." (PMID 28665978, 2017). "Jak1 and Tyk2 degradation was viral-replication dependent, as infection with UV-inactivated hMPV failed to affect Jak1 and Tyk2 cellular levels." (PMID 21949722, 2011). "However, when LGTV infection occurred prior to IFN addition, phosphorylation of STAT1, STAT2, Tyk2, and Jak1 were all inhibited, suggesting that LGTV must establish a productive infection to counteract the IFN response." (PMID 21994750, 2011). "Although not efficacious for all patients, JAK1 or p19 inhibition, which modulate IFN pathways, may be effective in those anti-TNF nonresponders for whom clinical benefit outweighs infection-associated safety risks." (PMID 39438660, 2024). "We also observed changes in the abundance of m6A-modified JAK1 and STAT6 transcripts, which are also part of the JAK/STAT signaling pathway and may functionally interact with each other as part of the host cell response to infection." (PMID 36625663, 2023). "K8NPs stimulated the late signaling pathway, including JAK1/2, which may be induced by an EGFR- or IFN-γ–mediated pathway, and affected the induction of hBDs, which kills S. aureus and reduces its intracellular infection." (PMID 38004123, 2023). "In addition, when compared to co-incubation with the inhibitor alone, the infection rate of either JAK1 or STAT1 inhibitor treatment was significantly higher without RNase 7 pretreatment (p < 0.01, compared to AMP plus JAK1 or STAT1 inhibitor treatment, respectively)." (PMID 35563546, 2022).
infection (continued). "While JAK1 shows only marginal expression in A549 cells, there was a clear activation of JAK2 (phosphorylation of JAK2 at Y1007/Y1008) and its downstream target signal transducer and activator of transcription 3 (STAT3, phosphorylation at Y705) detectable upon WSN infection." (PMID 32866218, 2020). "Neither ncpBVDV infection nor IFNT alone altered JAK1 mRNA expression." (PMID 31861316, 2019). "During early infection (within 24 h in cell culture), the virus blocks the phosphorylation and nuclear translocation of STAT1; however, during late infection, the virus modulates the IFN-1 response by inducing the downregulation of JAK1 and Tyk2 protein expression." (PMID 27367734, 2016). "In addition, except for 4 of the regulatory genes (IRF4, JAK1, NFATC4 and STAT6), many of the other genes in this pathway were only transiently expressed at 2 (IL4R and PTPRC) or 4 and/or 8 (IL13, IL4 and CEBPB) weeks post-infection." (PMID 23448601, 2013). "Whilst infection of monocytes with EBV for 20 hours led to the phosphorylation of Jak1, STAT1 but not Tyk2 nor STAT2, increased phosphorylation of these proteins could not be observed upon restimulation of infected cells with IFNα." (PMID 20689596, 2010). "In addition, using CRISPR/Cas9 gene editing, we showed that the transient KO of JAK1 highly enhanced VSVΔ51 infection in 786-O cells and 4-OI could not promote it further." (PMID 38750019, 2024). "We next tested the JAK1/2 inhibitor ruxolitinib, which acts upstream of STAT1 and is broadly effective at preventing IFN (and another cytokine) signaling, and again observed that JAK1/2 inhibition did not rescue the infection defect associated with p38β knockdown." (PMID 37345956, 2023). "Similarly, infection with live, but not UV-inactivated virus, led to significant reduction of Jak1 and Tyk2 cellular levels, indicating that inhibition of Jak/STAT pathway is dependent on viral replication and gene transcription, which is lost upon UV irradiation." (PMID 21949722, 2011). "Next, we examined the activation of the key kinases p38 MAPK, ERK and the final downstream effector target of JAK1/2 pathway i.e., STAT3 in uninfected non-senescent and senescent cells and at 1h and 16h post-infection." (PMID 34746026, 2021). "This was particularly apparent in experiments using the JAK1/2 inhibitor ruxolitinib, which potently reduced the ISG response to viruses with defective viral capsids, but had no impact on infection read out by GFP positivity of the cells (Figs EV2C and EV4E, and EV5A)." (PMID 32852081, 2020). "Additionally, SOCS proteins that can downregulate JAK and STAT1 phosphorylation are actually induced by Toxoplasma infection, and the expression of the protein tyrosine phosphatases (PTPs) that are known to dephosphorylate JAK1, JAK2, or STAT1 are not downregulated by infection alone." (PMID 23240025, 2012).
hematological malignancies (18 papers, 2012 to 2026). "Deep mutagenesis of JAK1 with cytidine and adenine base editors, combined with pathway-wide screens, reveal loss-of-function and gain-of-function mutations, including causal variants in hematological malignancies and mutations detected in patients refractory to ICB." (PMID 36669486, 2023). "Ruxolitinib, a clinically approved JAK1/2 inhibitor used in the treatment of hematologic malignancies and inflammatory conditions, has been shown to interfere with the function of cytotoxic T lymphocytes (CTLs)." (PMID 40649901, 2025). "Ruxolitinib, a JAK1/2 inhibitor that is already approved for use in hematologic malignancies, is a therapy of interest in ENKTL, given pre-clinical work that JAK1/2 inhibition can disrupt JAK/STAT signaling in STAT3-mutated or overexpressed ENKTL." (PMID 36900160, 2023). "Both JAK1 and JAK3 can bind to IL-2R, IL-4R, IL-7R, and IL-15R.34,217 Gain-of-function mutations in four Janus kinases play roles in hematologic malignancies." (PMID 34824210, 2021). "Further genes simultaneously affected by sCNAs and SNVs/indels, included POT1, JAK1, and PCM1, which are all linked to hematologic malignancies." (PMID 29449575, 2018). "JAK mutations have also emerged in other hematologic diseases, and the majority of the pathogenic mutations in JAK2 (also in JAK1 and JAK3) localize in or near the pseudokinase domain." (PMID 26377485, 2016). "Because numerous JAK1 and JAK3 variants associated with hematological malignancies are located within dynamic structural loops, it is conceivable that these regions may be more susceptible to allosteric drug-targeting." (PMID 37834019, 2023). "Besides, the efficacy of ruxolitinib, a JAK1/2 inhibitor, or ibrutinib, a Btk inhibitor, has been described in several hematological malignancies, and more studies are ongoing." (PMID 27896224, 2016). "The JAK family includes JAK1, JAK2, JAK3, and Tyk2, and their inhibition is known to be therapeutic for many autoimmune and hematological diseases." (PMID 39742289, 2024). "Expression of JAK1/2 and STAT3 in latently infected cells from both lines was suggestive of an IL-6 response axis (IL6(R)/JAK/STAT3) known to be activated in hematologic malignancies." (PMID 39446925, 2024). "FERM domains of JAK1 and JAK3 are identified as a hot spot for hematologic malignancies." (PMID 37834019, 2023).
adenocarcinoma (7 papers, 2018 to 2024). A common cancer characterized by the presence of malignant glandular cells. "Genomic loss of JAK1 occurs in some adenocarcinoma and CRPC cell lines, explaining why some cell lines, particularly adenocarcinoma cell lines, with a deficient IFN-γ response fail to produce PD-L1/IDO-1." (PMID 33692219, 2021). "Loss of JAK1 was shown to stimulate human adenocarcinoma cells unresponsive to IFN, suggesting that immune resistance induced by JAK1 deficiency is related to IFN signaling." (PMID 30837996, 2019). "For the patient with PAF and adenocarcinoma in the same lobe, SNVs of HER2 were detected in adenocarcinoma, and SNVs of JAK1 and PTPN11 genes were found in PAF, suggesting that PAF is unlikely to be related to the occurrence of adenocarcinoma." (PMID 34350112, 2021). "JAK1 gene amplification was found in 18.2% of the neuroendocrine samples, and in 6.3% of the adenocarcinoma samples." (PMID 29441069, 2018). "Moreover, JAK1 inhibition has been shown to reduce the progression of KRAS mutant adenocarcinoma in mice." (PMID 38706597, 2024). "This new connection between KRAS and JAK-STAT signalling might be of clinical relevance as JAK1 inhibition has been shown to reduce murine KRAS mutant adenocarcinoma progression." (PMID 37627169, 2023). "It is worth noting that p27/JAK1/STAT3 axis is crucial in lung squamous carcinoma carcinogenesis but not adenocarcinoma." (PMID 39099000, 2024).
hematopoietic cancer (6 papers, 2015 to 2025). "This study sought to understand the molecular-structural basis of gain-of-function (GoF) variants and hematopoietic neoplasms using the established full-length mouse JAK1 structure." (PMID 37834019, 2023). "An overlay of full-length human JAK1 and JAK3 shows a clustering of FERM-SH2 domain hematopoietic neoplasm variants along the surface pointing away from the center of the JAK dimer." (PMID 37834019, 2023). "Nuclear translocation is often mediated through a nuclear localization sequence (NLS), which has been identified in JAK1 and is required for nuclear translocation of JAK1 in hematopoietic cancer cells." (PMID 33466582, 2021). "For instance, bortezomib and ruxolitinib (a JAK1/2 inhibitor targeting STAT3) have shown promise in other hematologic cancers and may enhance therapeutic strategies when combined with BCR inhibitors." (PMID 40129242, 2025). "Somatic mutations in JAK1, required for immune cell signaling in response to interferon gamma (IFNγ), have been associated with several non-hematopoietic and hematopoietic cancer cell types but pathogenic mechanisms remain largely unexplored." (PMID 31552026, 2019).
bacterial infection (4 papers, 2010 to 2022). "The fact that both JAK1 and JAK2 are imperative in the signaling cascade required for MHC II cell surface expression is well established, and their abrogation leading to decreased MHC II has been seen in certain bacterial infections." (PMID 25690042, 2015). "Therefore, we concluded that, in myeloid cells, JAK1 is non-redundant for multiple aspects of the IFN-γ-response required to control intracellular bacterial infection." (PMID 36159783, 2022). "In addition, a further 12 ISGs of 380 tested ISGs including STAT1, STAT2, JAK1, IRF9, IRF2, IRF7 are key elements of IFN signaling, and classical and well-known ISGs such as ISG15, PKR, MX1, IFIT1, PML, IFI27 play key roles in viral or bacterial infections." (PMID 30717477, 2019).
cardiovascular disease (3 papers, 2014 to 2025). "Cytokines, TNF α, IL-6, JAK1 and STAT3 as markers of inflammation response may play a major role in the risk for cardiovascular disease, which is also recognized as essential mediator of pathological aging." (PMID 25524239, 2014).
neurological disease (3 papers, 2021 to 2025). "JAK1 and JAK2 have been extensively studied and seem to play the most predominant role, as mice knocked out (KO) for JAK1 exhibit severe lymphocyte damage and neurological disease, and JAK2 KO mice die in utero due to impaired hematopoietic functions." (PMID 41463071, 2025). "Apart from JAK1, these genes are widely expressed and generally involved in cell cycle, growth or differentiation without direct correlates to neurological disease." (PMID 33674671, 2021). "However, while appreciating that any improvement in neurological status is of importance, we consider it now evident that JAK1/2 inhibition does not afford major benefits in terms of neurological disease in the majority of patients with AGS so far treated." (PMID 37171742, 2023).
inflammation (2 papers, 2022 to 2025). Aberrant reaction of the microcirculation characterized by movement of fluid and leukocytes from the blood into extravascular tissues. "Accordingly, several studies have indicated that JAK1/STAT3 is associated with pulmonary inflammation." (PMID 36698809, 2022).
vasculopathy (2 papers, 2023 to 2025). "We demonstrate in a mouse model of CAV that blockade of JAK1 and JAK2 signaling with Ruxolitinib reduces vasculopathy and prolongs allograft survival." (PMID 41333445, 2025).
brain disorder (1 paper, 2022). A disease affecting the brain or part of the brain. "Clinical studies have also shown that dysregulation of the expression of JAK1 and JAK2 associates with brain inflammatory processes and neuronal or glial survival, which are consequently involved in most brain disorders including the pathogenesis of AD." (PMID 35701806, 2022).
JAK1 also shares sentences with these, for which no sentence is quoted: Thrombocytopenia (10 papers); neutropenia (8); juvenile idiopathic arthritis (7); hepatitis B (4); metastatic cancer (4); nasopharyngeal carcinoma (4); pancreatic ductal adenocarcinoma (4); Aicardi-Goutières Syndromes (3); essential thrombocythemia (3); systemic sclerosis (3); viral diseases (3); acute respiratory distress syndrome (2); bone inflammation disease (2); breast (2); chronic kidney disease (2); clear cell renal cell carcinoma (2); colon adenocarcinoma (2); cryptococcosis (2); cutaneous lupus erythematosus (2); digestive system cancer (2); enterocolitis (2); Erythema (2); esophageal squamous cell carcinoma (2); gastroenteritis (2); Hemophagocytic lymphohistiocytosis (2); Hepatosplenomegaly (2); hidradenitis suppurativa (2); latent infections (2); measles (2); metabolic disease (2).
A further 130 diseases each share a sentence with JAK1 in 2 papers or fewer.